MTOR (mechanistic target of rapamycin kinase)
Diseases named in the same sentence as MTOR in open-access papers (continued):
Sharing a sentence is not in itself a finding about the gene and the disease.
epilepsy (continued). "Increased mTOR activity has been suggested to play a role in the epileptogenesis of temporal lobe epilepsy, with inhibition of mTOR via rapamycin decreasing neuronal cell death, neurogenesis, mossy fiber sprouting, and the development of spontaneous epilepsy in a rat model." (PMID 34658792, 2021). "Altered mTOR signalling has also been associated with ASD, schizophrenia, depression and epilepsy." (PMID 34680906, 2021). "Moreover, recent studies have further confirmed the substantial therapeutic potential of targeting the mTOR signaling pathway in drug-resistant epilepsy." (PMID 34805265, 2021). "Importantly, we observed that almost all transcriptional changes were reversed by rapamycin treatment, supporting that excessive mTOR signaling is the main dysfunction leading to epilepsy." (PMID 34877936, 2021). "Microglial mTOR activity is elevated in human epilepsy and animal models." (PMID 33472865, 2021). "miRNA-155 provokes the beginning of convulsions in epilepsy via the PI3K/Akt/mTOR pathway." (PMID 34832986, 2021). "In addition to various antiepileptic drugs, current standard treatments for epilepsy in case of TSC include direct inhibition of mTOR pathway activity with everolimus." (PMID 34298906, 2021). "Meng X.F., Yu J.T., Song J.H., Chi S., Tan L. Role of the mTOR signaling pathway in epilepsy." (PMID 34901706, 2021). "Investigations in cerebral organoids of TSC2 patients with drug resistant epilepsy and cortical tuber development have shown mTOR hyperactivity, increased proliferation and subsequent generation of cortical tubers in vitro specifically in a caudal late interneuron progenitor population." (PMID 34828352, 2021). "To assess whether the increased amount of action potentials in CA1 pyramidal neurons is mTOR dependent and reversible after epilepsy has started, we measured excitability in 2 rapamycin treatment conditions." (PMID 34877936, 2021). "In this context, chronic BBB dysfunction and epileptogenesis after status epilepticus (SE)–induced epilepsy could be reduced via treatment with rapamycin, pointing toward a more general role of mTOR-dependent BBB remodeling during epileptogenesis in epilepsy." (PMID 33041976, 2020). "In the present manuscript, we provide an update on the role of mTOR in epileptogenesis while discussing possible biochemical and molecular mechanisms bridging alterations of cell-clearing systems with epileptogenesis and epilepsy-induced neuronal alterations." (PMID 32121250, 2020). "Later studies using different animal models of genetic and acquired epilepsies demonstrated that a hyperactivated mTOR seems to play a crucial role in epileptogenesis and that mTOR inhibitors decrease the development of seizures preventing epileptogenesis-related mechanisms." (PMID 33202963, 2020). "Consequently, mTOR inhibitors have been proven effective in reducing the frequency of epilepsy in TSC patients besides antiepileptics." (PMID 33123575, 2020). "If there is an increase in mTOR cascade function, epilepsy also increases." (PMID 33250850, 2020). "Similarly, in other epilepsies characterized by mTOR activation, such as FCD, TLE, and Rasmussen encephalitis, increased expression of microglial markers has been found in the respective brain lesions." (PMID 33041976, 2020). "All previous results support the notion that a hyperactivated mTOR signaling may contribute to epilepsy and that mTOR inhibitors could act as potential antiepileptogenic or antiepileptic treatments." (PMID 33202963, 2020). "The expression level of phosphorylated mTOR (p‐mTOR) may reveal a mechanistic pathway in epilepsy formation and its severity." (PMID 32140643, 2020). "The key role of the mTOR pathway in epileptogenesis is best exemplified by tuberous sclerosis complex (TSC) and focal cortical dysplasia (FCD), the most common genetic causes of epilepsy." (PMID 32121250, 2020).
epilepsy (continued). "DEPDC5 gene (OMIM∗614191) encodes disheveled Egl-10 and pleckstrin (DEP) domain containing protein 5, which forms part of the GTPase-activating protein activity toward RAG complex 1, a repressor of the mammalian target of rapamycin (mTOR) signaling pathway that is closely related to epilepsies." (PMID 32848577, 2020). "Therefore, alternative pharmacological approaches to selectively modulate the mTOR pathway seem to be preferable for treating epilepsy." (PMID 33202963, 2020). "It has been reported that mTOR activity was increased in animals with epilepsy." (PMID 33519354, 2020). "We aimed to investigate the expression of proteins that might relate to epilepsy—mammalian target of rapamycin (mTOR) and semaphorin 3F (SEMA3F), respectively—for establishing the mechanism and explaining the antiepileptic effect of GR." (PMID 32140643, 2020). "Moreover, in TLE patients with glial scarring due to drug-resistant epilepsy, mTOR activation was mostly found in microglia and to a lesser extent in astrocytes." (PMID 33041976, 2020). "In the present study, we generated a novel epilepsy mouse model based on mTOR hyperactivation." (PMID 31978189, 2020). "This study suggests that our melanocyte-lineage mTOR hyperactivation mouse is a novel animal model of epilepsy, which may promote the progress of both epilepsy and neurophysiology research." (PMID 31978189, 2020). "The mTOR pathway is a frequent target of epilepsy treatment." (PMID 31133639, 2019). "Moreover, S6 phosphorylation is controlled by phospho-Akt, and higher activity of the mTOR pathway has been demonstrated in both animal models of epilepsy and patients." (PMID 31450553, 2019). "It has been demonstrated that hyperactivation of mTOR signaling is a common occurrence in epilepsy." (PMID 31427480, 2019). "The α-isoform of PI3K which is a pivotal modulator of PI3K/AKT/mTOR signaling pathway, responsible for neurological disorders like epilepsy, found as a potential target molecule against these 17 semi-synthesized PBS compounds using in silico ligand-based pharmacophore mapping and target screening." (PMID 31133639, 2019). "Understanding the mechanism of the effect of osthole on PI3K/AKT/mTOR expression of microglia may elucidate important pathways that may be targeted to treat epilepsy." (PMID 30922159, 2019). "The evaluated parameters indicated osthole inhibits proliferation and induces apoptosis in BV-2 microglia cells in kainic acid-induced epilepsy may be via modulating PI3K/AKt/mTOR signalling way." (PMID 30922159, 2019). "Consequently, changes in mTOR signaling have been correlated with a spectrum of neuropathologies, such as epilepsy, intellectual disability, autism, brain injury, brain tumor formation and neurodegeneration." (PMID 31114481, 2019). "Dual inhibitors of phosphoinositide 3-kinase (PI3K) and mTOR (NVP-BEZ235) could be more effective than rapamycin alone to prevent epilepsy development." (PMID 31798512, 2019). "The higher diagnostic yields were from ion channel-related genes and mTOR pathway-related genes, which does not significantly differ from the results of previous studies on familial or early-onset epilepsies." (PMID 31875159, 2019). "Thus, our current data coupled with several other studies demonstrating the effectiveness of mTOR inhibitors in preventing or reducing seizures in different models of epilepsy suggest possibility of mTOR pathway as a promising therapeutic target for FCD1,11." (PMID 30568293, 2018). "On the other hand, administration of mTOR inhibitors may be beneficial for a variety of neuropsychiatric alterations encompassing neurodegeneration, brain tumors, brain ischemia, epilepsy, autism, mood disorders, drugs of abuse, and schizophrenia." (PMID 30061532, 2018). "Furthermore, we present that de novo mutations in a key regulator of mTOR, RHEB, causes severe ID, epilepsy and megalencephaly in humans." (PMID 29051493, 2017).
epilepsy (continued). "Indeed, recent studies indicated that mTOR inhibition is a promising treatment for epilepsy in tuberous sclerosis complex (TSC) patients." (PMID 29051493, 2017). "Lastly, we determined whether the epilepsy of the Pten-cKO mice could be mitigated by controlling the hyperactive mTOR signaling with its inhibitor rapamycin." (PMID 26961412, 2016). "Selective genetic upregulation of mTOR activity in newborn granule cells leads to an epilepsy phenotype, and increased adult neurogenesis has been hypothesized to contribute substantially to epileptogenesis." (PMID 26640431, 2015). "Previous studies have indicated that the mammalian target of rapamycin (mTOR) signaling pathway may be important in the course of epilepsy and epileptogenesis, and may offer a promising molecular target in epilepsy therapy." (PMID 25891824, 2015). "CR might inhibit the activity of the mammalian or mechanistic target of rapamycin (mTOR) signaling cascade, which seems to participate crucially in the generation of epilepsy." (PMID 25814935, 2015). "Another unexpected commonality between neurodegenerative diseases and epilepsy may be a defect of autophagy due to dysfunction of the mammalian or mechanistic target of rapamycin (mTOR) signaling pathway." (PMID 25814935, 2015). "Rapamycin, a FDA-approved mTOR inhibitor, has been thoroughly studied in models of epilepsy." (PMID 26248290, 2015). "Indeed, there is extensive human and mouse evidence that elevated mTOR signaling is epileptogenic although the mechanisms for the epilepsy are incompletely understood." (PMID 26633882, 2015). "Interestingly, oxamate inhibits not only LDH but also mTOR pathway, which is the major signaling pathway in both genetic and acquired epilepsies." (PMID 26217188, 2015). "The ability of rapamycin to block mossy fiber sprouting in acquired epilepsy models, and the apparent inability of increased mTOR signaling to drive mossy fiber sprouting unless a threshold level of KO cells is met, raises interesting questions about when and where rapamycin is acting." (PMID 24672426, 2014). "In this study, we performed a direct head-to-head comparative analysis of neurons lacking one of two genes that are both repressors of the mTOR signaling pathway and whose loss causes epilepsy and autism in animal models and humans." (PMID 24574959, 2014). "It is notable, therefore, that hyperactivation of mTOR signaling is present in acute seizure, status epilepticus, traumatic brain injury, hypoxia, and in vitro models of epilepsy." (PMID 24672426, 2014). "Additional subtle effects of increased mTOR signaling in acquired epilepsy may include the burst of neurogenesis observed following epileptogenic brain injury in rodents." (PMID 24672426, 2014). "If more evidence emerges of the anti-epileptogenesis and seizure-control capacity of mTOR modulators, it may be that such therapies will find application across a broader range of epilepsies." (PMID 25005575, 2014). "Interestingly, when PTEN was selectively deleted in granule cells (with resulting hyperactivation of mTOR), spontaneous epilepsy, granule cell hypertrophy and mossy fibre sprouting occurred." (PMID 25005575, 2014). "In addition to cancer, dysregulation of mTOR activity has been found in neural diseases, such as epilepsy, Parkinson’s disease, Alzheimer’s disease, and traumatic brain injury (TBI)." (PMID 24602288, 2014). "Our aim was to explore mTOR pathway activation in a range of epilepsy-associated pathologies and in lesion-negative cases." (PMID 25005575, 2014). "However, these previous studies in the kainate and pilocarpine models of SE and epilepsy have only assessed P-S6 at the S235/235 site, which can be phosphorylated in an mTOR-independent manner." (PMID 23536771, 2013). "Further studies are needed to assess the full potential of mTOR inhibitors for epilepsy treatment." (PMID 24044547, 2013).
epilepsy (continued). "As with epilepsy, the link between aberrant mTOR activation and autism is strongest in tuberous sclerosis complex; between 20 and 60% of tuberous sclerosis patients are diagnosed with autism, which may account for 1–4% of all autism cases." (PMID 24379984, 2013). "In addition, individuals with mutations in TSC1, TSC2, and PTEN, all of which influence cAMP activity and the MTOR pathway all display neurological findings and an increased prevalence of epilepsy." (PMID 24260271, 2013). "Rapamycin also prevents epilepsy in a mouse model of the tuberous sclerosis complex, alterations of which in general impact neuronal morphology and function as well more directly mTOR signaling." (PMID 24086344, 2013). "Animal models allow investigation of mTOR activation at the two earlier stages of epilepsy." (PMID 22761730, 2012). "The first suggestion that mTOR could be a potential therapeutic target for epilepsy came from studies using a mouse model of tuberous sclerosis complex." (PMID 22761730, 2012). "During disorders of epilepsy that can be a recurrent acute disability, mTOR inhibition may be beneficial." (PMID 23203037, 2012). "Thus, gaining insight into the spatio-temporal pattern of mTOR activation during the onset and progression of epilepsy will increase our understanding of the potential anti-epileptogenic role of mTOR inhibitors." (PMID 22761730, 2012). "Prior work linking HCFC1 mutations to GABAergic deficits in mice and radial glial abnormalities in zebrafish suggest a multifaceted mechanism, wherein mTOR may underlie neurodevelopmental phenotypes and potentially intractable epilepsy in cblX syndrome and other HCFC1-related seizure disorders." (PMID 41562862, 2025). "Additionally, chronic seizure models in adult zebrafish could assess whether mTOR inhibition alters epilepsy progression or comorbid cognitive deficits, which are hallmarks of cblX syndrome." (PMID 41562862, 2025). "Here, we deleted the mTOR pathway inhibitor Pten from a subset of excitatory hippocampal granule cells, modeling the mosaic loss of mTOR regulators now identified in focal cortical dysplasia Type II (FCDII), tuberous sclerosis complex, and numerous other conditions associated with epilepsy." (PMID 39497922, 2024). "Therefore, exploring the key regulatory signaling pathways involved in epilepsy is of great importance, and inhibition of the mTOR signaling pathway could be a promising therapeutic avenue against the development of epilepsy." (PMID 38365306, 2024). "We subsequently hypothesized that the reduced expression of these genes induced by LEV treatment reduces the hyperactivation of the PI3K/AKT/mTOR pathway, which might reduce the amount of apoptosis, neurogenesis, mossy fiber sprouting, and hyperexcitability in epilepsy." (PMID 38338984, 2024). "Therefore, the role of mTOR signaling in AD and epilepsy is currently under investigation." (PMID 38999445, 2024). "The observation of EEG abnormalities in some children treated prenatally raises the question of whether mTOR inhibition, particularly when administered late in gestation, can adequately prevent or mitigate the development of epilepsy and other neurological deficits." (PMID 39518472, 2024). "As the authors conclude, the observation that a deficiency of mTOR signaling in microglia increases seizure susceptibility contrasts the prevailing opinion that hyperactivation of mTOR is epileptogenic and might explain the inconsistent effect of rapamycin in animal models of epilepsy." (PMID 36769250, 2023). "To further test the generality of the hypothesis that ASO-mediated inhibition of mTORC2 can suppress seizures across a wide range of causative etiologies, we studied two genetic models of spontaneous recurrent seizures: Kcna1-null mice and a “humanized” MTOR gain-of-function model of epilepsy." (PMID 37963879, 2023). "However, the role of the downstream mTOR pathway in epilepsy pathogenesis is far less studied." (PMID 36675042, 2023).
epilepsy (continued). "Thus, mTOR‐dependent cell‐clearing systems are now taking centre stage in the field of epilepsy." (PMID 37737447, 2023). "Moreover, overexpression of miR-155 significantly suppressed the BDNF and TrkB protein expression and exhibited a neuroprotective effect on epilepsy-induced neuronal damage via the PI3K/Akt/mammalian target of rapamycin (mTOR) signaling pathway in patients with MTLE." (PMID 35916975, 2022). "Thus, the overemphasized effects of mTOR for autophagy activity may mislead the interpretation of mTOR-related experimental results, and ignore the autophagy-unrelated contribution of mTOR to epilepsy." (PMID 36078029, 2022). "Recent studies have shown that epilepsy surgery may be effective in patients with mutations involving specific genes (mTOR pathway genes as an example), but this has not been demonstrated in patients with other gene mutations." (PMID 35492509, 2022). "While the dysregulation of mTOR signaling pathways may manifest differentially across seizure disorders, the many connections between tau and mTOR highlight the significance of maintaining an optimal ratio of dephosphorylated and phosphorylated tau through balanced kinase/phosphatase regulation." (PMID 35923547, 2022). "Furthermore, mutations in other genes in the PI3K/Akt/mTOR pathway, including AKT3, PIK3CA, and DEPDC5, may also cause epilepsy." (PMID 34040629, 2021). "Because IGF1 acts to increase Akt/mTOR signaling and mTOR inhibition is effective in reducing certain hallmarks of epilepsy and posttraumatic epilepsy, it is important to determine whether IGF1-based therapies for TBI increase the risk for posttraumatic epilepsy." (PMID 34095131, 2021). "Additionally, rapid and transient mTOR activation was observed in the hippocampus and neocortical tissue after status epilepticus was induced and was followed by a subsequent increase in mTOR during epileptogenesis and continued post-epilepsy onset within several rodent models." (PMID 34658792, 2021). "Therefore, transient treatment with mTOR inhibitors during brain development might prevent the formation of a cortical malformation and could consequently reduce the chances of developing epilepsy." (PMID 34038402, 2021). "Moreover, MCD animal models may offer an elegant way of studying the transduction of signal linking the mTOR signaling cascade hyperactivation to neuronal hyperexcitability, ultimately leading to epilepsy." (PMID 33551717, 2020). "Thus, post-transcriptional loss of UCHL1 following SE is deleterious to neuronal survival and may contribute to epileptogenesis and epilepsy-induced brain damage, while mTOR inhibition can restore these alterations by rescuing UPS beyond autophagy." (PMID 32121250, 2020). "In some cases, mTOR inhibition has mitigated acute or chronic seizures, and, in other models, the blockade of mTOR by rapamycin had minimal effect on seizures or epilepsy development, suggesting that the effects of rapamycin might only be restricted to certain experimental models and conditions." (PMID 33202963, 2020). "Accumulating evidence indicates that mTOR also participates in epileptogenesis associated with other forms of genetic or acquired epilepsy such as Lafora disease (LD), temporal lobe epilepsy (TLE), traumatic brain injury, and experimental epilepsy induced by chemoconvulsive compounds." (PMID 32121250, 2020). "Thus, mTOR-dependent cell-clearing systems are now taking center stage in the field of epilepsy." (PMID 32121250, 2020). "Studies have shown that the inhibition of mTOR can induce autophagy, and mTOR-regulated autophagy can improve the symptoms of epilepsy and neuroinflammation in animal models of TBI, so we next investigated whether mTOR-regulated autophagy in the SCI mouse model also played a neuroprotective role." (PMID 32404105, 2020).